TIGIT (T cell immunoreceptor with Ig and ITIM domains)
Diseases named in the same sentence as TIGIT in open-access papers (continued):
Sharing a sentence is not in itself a finding about the gene and the disease.
tumor (continued). "The pathogenic bacterium F. nucleatum secretes Fap2 protein, which engages the inhibitory receptor TIGIT to arrest natural killer cell activation within the tumour microenvironment." (PMID 38750176, 2024). "Targeting CD155/TIGIT pathway suppressed tumor progression and improved survival in tumor bearing mice." (PMID 38216949, 2024). "Our results demonstrated the reversal of Granzyme B and IFNγ inhibition by CD8 + T cells from tumor tissues following TIGIT blockade." (PMID 38216949, 2024). "LAG3 and TIGIT were more widely dispersed in the tumor location, and their expression levels rose with increasing distance from the tumor." (PMID 39256364, 2024). "Aspirin can induce apoptosis of Tregs via the TIGIT pathway, improving effector T cell function, ultimately resulting in tumor inhibition." (PMID 39113892, 2024). "There is evidence that blocking TIGIT and PD-1 leads to significantly increased cell proliferation, degranulation, and cytokine production by tumor-specific T cells." (PMID 38893211, 2024). "Immunofluorescent studies showed that TIGIT was detectable on tumor-infiltrating T cells in ~ 40% of RCC patient samples, although only a small subset had ≥ 5% TIGIT-positive T cells." (PMID 39105820, 2024). "In a GBM mouse model, treatment with anti-TIGIT/anti-PD-1 resulted in increased survival of the mice, reduced tumor volume, and increased immune infiltration in tumor lesions compared to single ICBs or isotype treatments." (PMID 38339353, 2024). "Accordingly, we observed an increase in TIGIT expression on NK cells from both the PB and tumor compartments of CRC pts." (PMID 39126041, 2024). "In mouse models, the TIGIT and PD-1 pathways are mechanistically interdependent, and co-blockade of TIGIT and PD-L1 has been shown to synergistically elicit anti-tumour T cell responses." (PMID 38418879, 2024). "Another study showed that anti-TIGIT prevented NK cell exhaustion and improved its immunogenicity in mouse models, resulting in tumor-specific T cell immunity and magnifying effects of combination immunotherapy with PD-1 and PD-L1." (PMID 38229100, 2024). "The administration of IL‐15 and anti‐TIGIT was tested using a transplanted tumour murine model and PDO model, which provided strong support for this conclusion." (PMID 38279870, 2024). "We found similar effects of Fc-active anti-TIGIT antibodies on the tumour microenvironment using flow cytometry." (PMID 38418879, 2024). "Here, we report the findings of a preclinical study of ZGGS15, a novel bispecific monoclonal antibody (BsAb) that can simultaneously inhibit LAG-3 and TIGIT alone or in combination with an anti-PD-1 antibody, exhibiting exceptional anti-tumor efficacy." (PMID 38724599, 2024). "Here, we expand on the idea, introducing a novel tumor-targeting anti-B7-H3 Fab and NK checkpoint-inhibiting anti-TIGIT Fab, resulting in a novel dual NK cell-targeting natural killer engager antibody." (PMID 38474651, 2024). "The inhibition of TIGIT significantly delayed tumor growth and enhanced antitumor immune responses in a mouse model of HNSC." (PMID 39052123, 2024). "The addition of anti-CD96 in combination with anti-PD-1, anti-CTLA-4, anti-TIGIT, or doxorubicin chemotherapy resulted in superior antitumor responses by enhancing T-cell activity and suppressing tumor growth." (PMID 38732242, 2024). "Accordingly, treatment with anti-TIGIT exerts anti-tumor function by activating CD8+ T cells, enhancing the cytotoxicity effects and population of T cells against cancer." (PMID 38229100, 2024). "The interaction between CD155 on tumor cells and TIGIT on CD8 + T cells appeared to disrupt the balance of glucose utilization, affecting the metabolic fitness of CD8 + T cells." (PMID 38216949, 2024). "Further analysis highlighted dynamic interactions between tumor cells andimmune cells, with significant changes detected in key signaling pathways, suchas TIGIT-PVR and MDK-SDC4." (PMID 39850495, 2024).
tumor (continued). "Anti-TIGIT treatment has been shown to decrease or deplete Tregs and reduce their suppressive activity, thereby contributing to anti-tumor immunity." (PMID 38891091, 2024). "It is reported that anti-TIGIT treatment exerts anti-tumor function by decreasing or depleting FoxP3+ Tregs." (PMID 38229100, 2024). "This engineered VV worked as a virus, replicated in tumor cells, lysed tumor cells, and secreted the anti-TIGIT scFv." (PMID 38229100, 2024). "Altogether, these findings suggest that TIGIT plays a suppressive role in anti-tumor immunity in cancer patients." (PMID 38638433, 2024). "Currently, the primary mechanisms of regressive tumor effects are PD-1 and, more recently, additional pathways such as Lag-3, TIGIT, and Tim-3, which directly target and reinvigorate Tex cells." (PMID 38460046, 2024). "The TIGIT knockout effect was studied by Zhang and colleagues, demonstrating positive outcomes regarding NK cell protection and tumor immunity in mouse models." (PMID 39339180, 2024). "These inhibitors represent promising approaches to counteract TIGIT-mediated immune suppression and enhance anti-tumor immunity in cancer patients." (PMID 39275127, 2024). "The outcome of single TIGIT blockade has exhibited limited or moderate antitumor effectiveness in experimental tumor models and in enhancing the in vitro functionality of human tumor-infiltrating CD8+ T cells." (PMID 38375475, 2024). "The antitumour effects in Tigit−/− mice were abolished when depletion of CD8+ T cells, rather than NK cells, CD4+ T cells, or Tregs, indicating that CD8+ T cells are essential for inhibiting tumour growth when TIGIT is depleted." (PMID 38279870, 2024). "The potential role of TIGIT in regulating the pathogenesis of LUAD was addressed through a murine model with transplanted tumours constructed in Tigit−/− mice." (PMID 38279870, 2024). "Genetic testing can assess the level of PD‐L1 expression in tumor cells, where vaccines, together with therapies focusing on the PD‐1 and TIGIT signaling pathways can help predict the potential response to immunotherapy." (PMID 38522008, 2024). "TIGIT has emerged as one of the most promising candidates for co-inhibition with PD-1/PD-L1 in tumor immunotherapy." (PMID 39064019, 2024). "We turned to preclinical models to study the effects of anti-TIGIT and Fc–FcγR interactions on tumour-infiltrating leukocytes." (PMID 38418879, 2024). "GFI treatment also reduced the mRNA and protein expression of TIGIT, and increased the expression of granzyme B to restore and activate T cell response in the tumor micro-environment." (PMID 38169590, 2024). "It has already been shown that blocking the inhibitory CD155/TIGIT checkpoint in the context of cancer leads to increased NK cell anticancer functioning against the tumor cells." (PMID 39329751, 2024). "Consistent with the scRNA-seq analysis, Fc-active TIGIT monoclonal antibodies drove increased cell surface expression of MHC-II on tumour myeloid cells, including dendritic cells, macrophages and monocytes." (PMID 38418879, 2024). "TIGIT has been defined as a novel target for cancer immunotherapy and is up-regulated in tumor-specific CD8 + T cells." (PMID 39033098, 2024). "When bound by CD155, TIGIT inhibits NK cell antitumor activities and benefits the survival and proliferation of the tumor cells." (PMID 39329751, 2024). "Recently, the importance of CD226 in tumor immunity has emerged, particularly in the context of anti-TIGIT therapy." (PMID 39349829, 2024). "In preclinical models, anti-TIGIT monoclonal antibodies activated tumour and circulating myeloid cells through engagement of Fc receptors, and did so synergistically in combination with anti-PD-L1 antibodies." (PMID 38418879, 2024).
tumor (continued). "Early clinical trials have shown that combining TIGIT inhibitors with other immunotherapies, such as PD-1/PD-L1 blockers, can lead to synergistic effects, resulting in increased tumor regression and prolonged survival." (PMID 39796695, 2024). "Only one report has shown that the expression of PVR, PVRL2, TIGIT, PD-1, and PD-L1 in lung adenocarcinoma is heterogeneous within and between tumors and varies according to tumor growth patterns, so future reports are expected." (PMID 39156900, 2024). "In several human tumor types, TIGIT and programmed cell death protein-1 (PD-1) are co-expressed by tumor antigen-specific T cells and tumor-infiltrating lymphocytes (TILs)." (PMID 38451273, 2024). "Expression of TIGIT was increased in tumor-infiltrating T cells, especially in DUSP4hi CD4 and CD8 T cells, compared to reference T cells from blood." (PMID 38181797, 2024). "Another interesting gene that is upregulated in Tregs with LOY is TIGIT, an immunosuppressive receptor found on tumour-infiltrating NK cells, CD8+, CD4 + and regulatory T cells, with highest abundance in the latter." (PMID 38443832, 2024). "Together, these data indicated that anti-TIGIT antibodies can engage activating Fc receptors to activate tumour macrophages, positively modulate tumour CD8+ and CD4+ T cells, and inflame circulating non-classical monocytes." (PMID 38418879, 2024). "TIGIT is expressed by tumor-infiltrating lymphocytes, such as CD4+ and CD8+ T cells, as Gur and colleagues demonstrated." (PMID 39872848, 2024). "Recent studies of tumor-infiltrating T cells showed that the success of PD1 or TIGIT inhibition as immunotherapy depends on the presence of CD226 and TIGIT co-expressing T cells in the tumor." (PMID 38533515, 2024). "In vivo, PM-1022 demonstrates similar anti-tumor efficacy to the combination of anti-TIGIT and anti-PD-L1 mAbs, which is stronger than the single agents alone." (PMID 38257366, 2024). "CD3+ and CD11B+ splenocytes showed a similar trend of TIGIT expression, although less pronounced compared with the tumor (1.3% vs 0.86% CD3+p = 0.0456 and 2.7% vs 2.1% CD11B+p = 0.0117)." (PMID 38438420, 2024). "Immune checkpoint genes, including CTLA4, CD96, and TIGIT, are enriched in the first layer on the tumour side." (PMID 39350478, 2024). "Ligand–receptor pairs including CD99‐CD99 and ADGRE5‐CD55 were predominantly identified in interactions between CD8+ T cells and NK cells with malignant cells, while Tregs mainly crosstalk with tumour cells via the TIGIT–NECTIN2 interaction." (PMID 39601163, 2024). "In GBM patients, the significant upregulation of TIGIT expression in CD8+ T cells at the tumor site compared to healthy individuals has been reported." (PMID 38275876, 2024). "In agreement with previous reports, the addition of anti-CSF-1R to anti-PD-L1 + anti-TIGIT partially depleted macrophages from the tumour beds of treated mice and sustained tumour responsiveness to checkpoint inhibitors." (PMID 38418879, 2024). "TIGIT is a novel immunotherapy target, which has been identified as an immunosuppressive molecule through repressing effector anti-tumor immune cells in the cancer-immune microenvironment." (PMID 38273291, 2024). "Although TIGIT inhibition alone has shown less impressive antitumor effects, dual blockade of TIGIT with PD-1 has demonstrated almost complete tumor rejection in murine tumor models, which is supportive of further investigation in patients with cancer." (PMID 39697225, 2024). "CD96 interacts with PVR (CD155) expressed by tumor cells, similar to the interaction of TIGIT and DNAM1." (PMID 39339180, 2024). "In vivo results showed that ZGGS15 had better anti-tumor inhibition than single anti-LAG-3 or anti-TIGIT agents and demonstrated a synergistic effect when combined with nivolumab, with a significantly higher tumor growth inhibition of 95.80% (p = 0.001)." (PMID 38724599, 2024).
tumor (continued). "TRM cells within tumor tissues express multiple inhibitory receptors, with elevated PD-1 and TIGIT expression levels on CD8+CD103+ T cells impairing antitumor function." (PMID 39391310, 2024). "Gene set enrichment analyses have further elucidated the biological signaling pathways of TIGIT, highlighting its contribution to immune suppression within this unique tumor context ​​." (PMID 38342925, 2024). "LGALS3 expression showed a significant positive association with CD274, TIGIT, PDCD1, HAVCR2, CTLA4, LAG3, as well as PDCD1LG2 after adjustment for tumor purity in HCC." (PMID 38643145, 2024). "Experimental evidence suggests that blockade of TIGIT mitigates NK cell exhaustion and augments NK cell-mediated antitumor immunity in several murine tumor models." (PMID 39152301, 2024). "Our analysis aimed to better characterize expression patterns of the immune checkpoint protein TIGIT on tumor-infiltrating T cells in RCC." (PMID 39105820, 2024). "PVR expression was increased in surviving tumor cells after co-culture with TILs from the responder and inhibited TIGIT+ T cell activation." (PMID 39156900, 2024). "In this regard, gradual differences in the intimacy of the contact between tumor and NK cells probably account for varying levels of immune cell exhaustion, and presumably also for the varying clinical response to therapeutic TIGIT-blockade." (PMID 38967649, 2024). "Studies have shown an inverse correlation between CD226 and TIGIT or PD-1 in tumor-infiltrating CD8 + T cells (CD8+TILs)." (PMID 39349829, 2024). "Engagement of TIGIT on T cells downregulates T cell receptor complex components, impairing recognition of tumor antigens." (PMID 39105820, 2024). "Treatment with IL‐15 or anti‐TIGIT resulted in significant suppression of tumour progression; notably, treatment with IL‐15 exhibited the most significant inhibition of tumour growth in Tigit−/− mice." (PMID 38279870, 2024). "Twenty ADG tumors with matched normal brain tissues were further analyzed; the expression levels of CD47 and TIGIT in tumor tissues were higher than those in matched adjacent normal brain tissues (P < 0.0001)." (PMID 38404571, 2024). "In the context of cancer, TIGIT can inhibit the attack of other immune cells on tumor cells, thereby promoting tumor growth and metastasis, and has become an important target in cancer treatment." (PMID 38227081, 2024). "Some scholars also found that tumor-specific co-suppressor receptors (e.g., TIM3, LAG3, and TIGIT, etc.)are highly expressed in a subpopulation of tumor-infiltrating Tregs." (PMID 39329710, 2024). "LAG3+ T cells highly expressed LAG3 and CTLA4+ T cells highly expressed CTLA4 and TIGIT, which were also higher in tumor tissues than in normal tissues." (PMID 38604154, 2024). "Blocking TIGIT reduces NK cell exhaustion, inhibits tumor growth, and enhances the production of proinflammatory cytokines by NK cells, indicating its potential as a therapeutic target to boost the immune response against tumors." (PMID 39192980, 2024). "The Treg cells highly and specifically expressed TIGIT, a gene participating in the tumor immune escape and playing a key role in the pathological process of tumor progression as an inhibitory receptor indispensable to immunoregulation." (PMID 38443340, 2024). "The immune checkpoint T‐cell immunoglobulin and immunoreceptor tyrosine‐based inhibitory motif domain (TIGIT) has recently been highlighted as an appealing target for new tumour immunotherapies." (PMID 38279870, 2024). "Rongzhang Chen and colleagues discovered that cordycepin plays a critical role in the effective anti-tumour action of anti-TIGIT therapy by upregulating the expression of Cd226 on TILs." (PMID 38953102, 2024). "TIGIT is highly expressed predominantly in tumor-infiltrating T cells and plays a vital role in suppressing the activity of CD8+ T cells." (PMID 39156900, 2024).
tumor (continued). "According to Harjunpää and Guillerey, there are reports suggesting that TIGIT has the ability to hinder various stages of the cancer immunity cycle, which includes suppressing anti-tumor reactions." (PMID 39623397, 2024). "Although anti-PD-L1 monotherapy had little effect, anti-PD-L1 + IgG2a anti-TIGIT combination treatment inflamed tumour macrophages, amplifying the antigen-presentation gene program induced by anti-TIGIT antibodies alone." (PMID 38418879, 2024). "Gene expression analysis of tumour macrophages and monocytes revealed that IgG2a anti-TIGIT and IgG2b anti-TIGIT antibodies both increased the expression of antigen-presentation genes, with IgG2a anti-TIGIT antibodies having a greater effect." (PMID 38418879, 2024). "Percentages of TIGIT+ splenic and tumor-derived CD8+ T cells were comparable for the different vaccine groups and the different time points." (PMID 38932345, 2024). "TIGIT and PD-1 can be co-expressed in tumor-infiltrating lymphocytes, and inhibition of both checkpoint pathways leads to greater activation of CD8+ T cell effector functions." (PMID 39156900, 2024). "TIGIT binds with high affinity to the poliovirus receptor (PVR) and is associated with impaired T cell and NK cell function, as well as impaired anti-tumor immunity." (PMID 38451273, 2024). "There is now strong evidence that TIGIT regulates both T-cell-mediated and natural killer cell-mediated tumor recognition in vivo and in vitro." (PMID 39845973, 2024). "Tumour Treg cells also responded to Fc-active anti-TIGIT antibodies with downregulation of an immunosuppressive gene program, although this effect was independent of macrophages." (PMID 38418879, 2024). "To explore the potential impact of the tumour microenvironment on immune homeostasis between TIGIT, CD96 and CD226 in LUAD, we performed correlation analyses among these three receptors." (PMID 38279870, 2024). "Univariate analyses showed that age, tumor type, MGMT unmethylation, CD47, and high TIGIT expression were all associated with OS, whereas gender, tumor location, and pTERT mutations were unrelated to OS." (PMID 38404571, 2024). "To further validate these results, we proceeded to establish an in vivo mouse subcutaneous tumor-bearing model, where mice received intraperitoneal injections of either IgG or Anti-TIGIT." (PMID 38216949, 2024). "Our findings indicated that immune checkpoints (PDCD1, ENTPD1 and TIGIT), the T-cell exhaustion state-associated transcription factor TOX, and the gene DDX58 (transcriptional protein RIG-I) are co-expressed in tumour-infiltrating CD8+ T cells (Fig. EV1A–D)." (PMID 39322862, 2024). "TIGIT is a novel suppressive immune checkpoint that is essential in adaptive immune-mediated tumor progression and liver tolerance to infection and tumor cell invasion." (PMID 38890507, 2024). "TIGIT is an inhibitory receptor that can be upregulated by tumor cells and other cells in the tumor microenvironment." (PMID 38279258, 2024). "The CD155/TIGIT signaling pathway exerts immunosuppressive effects by exacerbating cellular exhaustion, leading to tumor immune evasion." (PMID 39227959, 2024). "IHC staining of GL261 tumor tissue revealed areas of CD3 and TIGIT co-localization, indicating that TIGIT is expressed among tumor-infiltrating T-cells." (PMID 38438420, 2024). "The putatively exhausted tumor-infiltrating NK cells (PD-1+TIGIT+) were significantly increased (5.8-fold change) compared to peripheral NK cells from CC patients." (PMID 39201462, 2024). "Anti-TIGIT monotherapies, including the mIgG2a-formatted monoclonal antibody, exhibited a limited effect on controlling tumour growth." (PMID 38418879, 2024). "By targeting TIGIT, inhibitors disrupt its immunosuppressive signaling pathways, aiming to enhance the activity of tumor-infiltrating T cells and improve anti-tumor immune responses." (PMID 39275127, 2024). "TIGIT is expressed at higher levels on infiltrating lymphocytes within CRC tumor tissue than adjacent." (PMID 39113892, 2024).